ADGRG2 (adhesion G protein-coupled receptor G2)
Description:
Adhesion G protein-coupled receptor (aGPCR) for steroid hormones, such as dehydroepiandrosterone (DHEA; also named 3beta-hydroxyandrost-5-en-17-one) and androstenedione. Involved in a signal transduction pathway controlling epididymal function and male fertility. Ligand binding causes a conformation change that triggers signaling via guanine nucleotide-binding proteins (G proteins) and modulates the activity of downstream effectors, such as adenylate cyclase. ADGRG2 is coupled to G(s) G proteins and mediates activation of adenylate cyclase activity. Also able to couple with G(q) G proteins in vitro. Together with CFTR, required to promote fluid reabsorption within efferent ductule.
Synonyms: He6; GPR64; TM7LN2; EDDM6; CBAVDX
Tractability: Antibody: UniProt places it where antibodies can reach, with high confidence; its Gene Ontology location is reachable by antibodies, with high confidence; UniProt predicts a signal peptide or a membrane-spanning region.
Target class: Family B G protein-coupled receptor; Membrane receptor
Gene: Protein-coding gene on chromosome X (18,989,307 to 19,122,956, reverse strand). Ensembl gene ENSG00000173698.
Subcellular location: Apical cell membrane
Subcellular location (Human Protein Atlas): Cytosol; Plasma membrane
Gene Ontology:
Molecular function: G protein-coupled receptor activity; protein binding; transmembrane signaling receptor activity
Biological process: adenylate cyclase-activating G protein-coupled receptor signaling pathway; phospholipase C-activating G protein-coupled receptor signaling pathway; spermatid development; G protein-coupled receptor signaling pathway; spermatogenesis; cell surface receptor signaling pathway
Cellular component: apical plasma membrane; cell surface; extracellular exosome; plasma membrane; membrane
Homologues: Orthologues: chimpanzee ADGRG2 (99% identical), macaque ADGRG2 (97% identical), dog ADGRG2 (85% identical), pig ADGRG2 (83% identical), rabbit ADGRG2 (82% identical), guinea pig ADGRG2 (81% identical), mouse Adgrg2 (81% identical), rat Adgrg2 (81% identical), tropical clawed frog adgrg2 (43% identical), zebrafish adgrg4b (20% identical). Paralogues in human: ADGRG6 (35% identical), ADGRG4 (33% identical), ADGRL3 (17% identical), ADGRL2 (17% identical), ADGRF5 (16% identical), ADGRE2 (16% identical), ADGRB2 (16% identical), ADGRL1 (15% identical), ADGRG1 (15% identical), ADGRB1 (14% identical), ADGRD1 (14% identical), ADGRE3 (14% identical), and 30 more.